CD4 (CD4 molecule)
Diseases named in the same sentence as CD4 in open-access papers (continued):
Sharing a sentence is not in itself a finding about the gene and the disease.
infection (continued). "The infection of C. trachomatis is tried to control by CD4 and CD8 cells." (PMID 34234859, 2021). "The lymphoid environment of the tonsil oral MALT makes these tissues highly susceptible to infection and establishment of HIV reservoirs; however, CD4+ T cell dysfunction in relation to oral residual immune activation in cART-treated patients has not been studied before." (PMID 34446704, 2021). "Patients with severe infections demonstrated lower levels of CD4+, CD19+, and CD146+ EVs than HD." (PMID 33925492, 2021). "Using CD4+ T-cell count trajectories modelled to account for seroconversion bias, we estimated infection year of newly HIV-diagnosed migrants residing in the United Kingdom (UK), Belgium, Sweden and Italy with a known arrival year and CD4+ T-cell count at diagnosis." (PMID 34414881, 2021). "Therefore, we performed intravital flow cytometry to determine the location at days 23, 27, and 33 after infection of CD4+ T cells in the lungs of B6 and pMT-10 mice." (PMID 34554927, 2021). "Notably, higher frequencies of colonic CD4+ T cells and lower Th17/Treg ratios prior to infection in controllers correlated with improved responses to ART and control of viral rebound." (PMID 34138927, 2021). "The CD4+ T-cell cytokine signature associated with the nonlethal infection model was defined by significant differences in IL2 and IL2-TNF cytokine populations observed in the interstrain comparisons between the lethal and nonlethal models." (PMID 34287349, 2021). "Indeed, we previously reported that intestinal DCs migrate from the lamina propria inside the colonic epithelium following exposure to R5 HIV-1 through a CCR5-dependent mechanism to capture the virus and transfer the infection to receptive CD4+ T cells." (PMID 34253821, 2021). "Furthermore, TEM represent a preferential HIV target during initial mucosal infection given their high propensity for infection, and their abundance in cervicovaginal tissue relative to the other memory CD4 T cell subsets." (PMID 33872331, 2021). "Thus, we adoptively transferred CD4+ T cells from donor mice that were L. sigmodontis-infected for 72 days, a time point when C57BL/6 mice already cleared the infection, into RAG2IL-2Rγ-deficient C57BL/6 mice one day prior L. sigmodontis infection." (PMID 34868049, 2021). "After 36 h, luminescence was measured to determine whether the presence of RBC viral traps prevented infection of CD4+ T cells." (PMID 33723514, 2021). "Moreover, as in macrophages, multimeric binding of host CypA to the incoming viral capsid blocks the interaction of huTRIM5α with the viral core, thereby preventing huTRIM5α-mediated restriction during CD4+ T cell infection." (PMID 33669846, 2021). "Interestingly, depletion of either CD8+ or CD4+ cells resulted in a transient increase in B lymphocytes within the liver 14 days post-infection." (PMID 33376758, 2021). "The result showed that HSV-2-related infections had lower CD4+ T-cell counts (p = 0.102; 3b)." (PMID 33824853, 2021). "To investigate the responding CD4+ T cell repertoire and response to helminths, we infected IL-44get reporter mice with the helminth N. brasiliensis and performed TCRβ sequencing on sorted IL-4-expressing CD4+ T cells from the lung and lung-draining mediastinal lymph nodes nine days after infection." (PMID 34106992, 2021). "We performed in-depth analyses of M.tb-specific CD4 T cell function, activation and memory phenotypes to identify immunological differences between individuals who recently acquired infection and those with persistent (remote) infection." (PMID 33610126, 2021). "Our study found a decreasing trend in LC CD4 T-cell numbers of PLHIV treated in primary infection." (PMID 34135912, 2021). "To test this hypothesis, we assessed CD4+CD161+ T cells for the ability to inhibit intracellular Mtb growth using an in vitro infection model as described by us and others." (PMID 33732233, 2021).
infection (continued). "Next, we wanted to determine whether CD4 depletion during the early stages of the vaccination regimen alters protection from infection." (PMID 34745131, 2021). "After an initial increase in overall T lymphocyte numbers in the 1st week of infection followed by decreased CD4 T lymphocytes at 1-month post-SIV infection, the T lymphocytes resolved to baseline by the 1-month time-point, which was maintained it throughout set-point viremia and treatment phase." (PMID 33717202, 2021). "As expected, however, mice given a secondary infection with Hulk had significantly reduced worm burdens compared to mice given a primary infection, but these mice still had significantly fewer activated 2W1S-specific CD4+ T cells than peptide-immunized mice." (PMID 34237106, 2021). "Interestingly, different CD4+ antigen specificities showed unique cytokine profiles, which were also distinct in post infection vs. vaccination conditions." (PMID 33854501, 2021). "HAS2KO fSFs also augmented the infection rate of purified CD4+ T cells." (PMID 33976386, 2021). "Importantly, we observed that infection with this strain significantly increased the differentiation state of the MPT70-specific CD4 T cells and diminished their ability to enter the infected lung tissue." (PMID 33879592, 2021). "We first assessed whether, among infection-naïve individuals, the phenotypes of spike-specific CD4+ T cells were different after the first and second doses." (PMID 34636722, 2021). "As summarized above, aP vaccine-induced immune responses can be distinguished from wP and natural infection-induced immune responses with its 1) weak Th1/Th17 polarizing CD4+ T cell immunity, 2) low induction of tissue resident memory T cells and possibly 3) low functional antibody responses." (PMID 35222350, 2021). "A distinct but comparable mechanism of IFN-I inhibition also occurs upon infection of CD4 T cells." (PMID 33872331, 2021). "However, it was appreciated from early experiments how important CD4+ T cell help was to the eventual resolution of LCMV Cl 13 infection and in the maintenance of antiviral CD8+ T cell responses throughout the exhaustion phase." (PMID 34696381, 2021). "CD4 T cells are key mediators of adaptive immune responses during infection and vaccination." (PMID 34177929, 2021). "In anti-neutrophil cytoplasmic antibody-associated vasculitis, a condition associated with increased infection-related mortality, the presence of subclinical CMV infection appeared to adversely affect the available functional CD4+ T-cell compartment, resulting in impaired immunity to other antigens." (PMID 33743617, 2021). "However, CD4+ T cells secreted almost 2-fold more IL-17 in the presence of DCs that had been pretreated with kyn and γHV-68, conditions that mimic in vivo infection with γHV-68 in BMT mice." (PMID 33491663, 2021). "The attenuation of IFN induction in the early stages of infection may result in the limited activation of CD4+ T cells that harbor HIV proviruses, and is thus less likely to lead to the transactivation of HIV promoter." (PMID 34696531, 2021). "APOE and SPP1 restrict HIVGKO infection in both Jurkat T cells and primary CD4+ T cells." (PMID 33504604, 2021). "Furthermore, there was a significant correlation between S1 and SMN CD4+-reactivity among those HCWs with verified infection at TP4 (p < 0.0001, r = 0.81)." (PMID 34795668, 2021). "Infection generates high frequencies of CMV-specific CD4 and CD8 T memory cells." (PMID 33679794, 2021). "In addition, MDV can transform latently infected CD4+ T-cells, resulting in T-cell lymphomas that are observed as early as three to four weeks post infection." (PMID 34673841, 2021). "Our results suggest that T-cell responses—as measured by cytokine expression—and the frequencies of SARS-CoV-2-specific central memory CD4+T-cells—indicative of the formation of the long-lived memory T-cell compartment—are comparably induced after infection and vaccination." (PMID 34960185, 2021).
infection (continued). "A higher CD4+ cell percentage was detected in G-NcSpain1H at 10 dpi, but the differences were not statistically significant due to a high variability observed between animals of this infection group." (PMID 34239816, 2021). "However, once infiltrated into the SG, CD4 T cells are attracted to sites of infection by CXCL9/10 gradients, produced by either myeloid or epithelial cells of the SG." (PMID 34959486, 2021). "While WT SMARTA CD4+ T cells expanded dramatically in response to LCMV Armstrong infection, Ddb1-deficient SMARTA CD4+ T cells failed to expand in the same hosts." (PMID 34526995, 2021). "PD-1+ T cells therefore represent a discrete component of the physiological CD4+ T cell response to infection and understanding of their unique properties is likely to be crucial for uncovering mechanisms to reverse CD4+ T cell exhaustion in pathological states." (PMID 33662046, 2021). "This early gamma response in the low dose infection alone could be representative of the protective role of CD4+ T lymphocytes in mediating macrophage activation via iNOS expression." (PMID 34484203, 2021). "Evaluation of infection-induced changes in CD4 T-cell differentiation at Day 7 revealed a strong phenotypic shift to Th1 effectors (CXCR3+), Th1 polarized Tfh cells (CXCR3+ CXCR5+) and Th1 Th17 (CXCR3+ CCR6+) CD4 T cells as demonstrated by tSNE plots constructed using flow data." (PMID 33483492, 2021). "Infection with Plasmodium parasites (P. yoelii 17XL, P yoelii 17XNL, P. chabaudi, P. vinckei, and P. berghei) causes increased PD-1 and LAG-3 expression by activated CD4 cells." (PMID 34067904, 2021). "As shown in the present study, the lack of DCIR contributes to a more effective priming of peripheral T cells with increased CD44 and reduced CD62L expression by CD4+ T cells together with an increased IFN-γ expression in the spleen during the early phase of TMEV infection." (PMID 34893671, 2021). "About 10 days post-infection (dpi), the virus establishes a latent phase primarily in CD4+ T-cells." (PMID 34673841, 2021). "The total CD4 T-cell count increased significantly from 14- to 100-days post-infection." (PMID 35186781, 2021). "However, ART does not provide cure due to a stable latent reservoir established early in the infection process in resting CD4+ T cells, macrophages and other cells." (PMID 34017334, 2021). "During infection with S. tm., in line with the observations from the eSPF mice, we detected increased frequencies and absolute numbers of IL-17A-IL-22+ and IL-17A+IL-22+ CD4+ T cells in cecal LPLs from S. tm. infected SFB colonized GF mice." (PMID 34566952, 2021). "Our findings indicate that CD4+ T cell-dependent infection of AMs is a route of infection that may explain the presence of T-tropic HIV in AMs despite inefficient cell-free infection." (PMID 33594125, 2021). "We then asked whether PLWH in infection wave two showed different CD4 T cell responses to SARS-CoV-2." (PMID 34608862, 2021). "Putting our observation in this context, we investigated whether Vpu-mediated CD47 downregulation would facilitate macrophage infection by promoting phagocytosis of HIV-1-infected CD4+ T cells." (PMID 34425695, 2021). "Prevention of infection can be achieved by induction of CD4+ T cells providing help to B cells to produce protective virus-neutralizing antibodies, whereas vaccine-induced CD8+ T cells support disease attenuation and protection against complications after infection." (PMID 34211021, 2021). "A mechanism of action to explain the requirement for CD4+ T cells at the early stage of infection may be that CD4+ T cells are needed to help CD8+ T cells develop into functional effector cells and/or to aid the production of virus neutralizing antibodies." (PMID 34066322, 2021).
infection (continued). "Furthermore, effector CD4+ T cells can migrate to the site of infection and protect against viral pathogens through the local production of cytokines (IFNγ and TNFα) and direct cytolytic activity mediated by perforin and FAS." (PMID 34066322, 2021). "Differences in epigenome-wide methylation were observed in CD4+ T cells isolated from individuals with varying degrees of control, suggesting that methylation status differs according to the progression of diseases state and control of infection." (PMID 34925380, 2021). "Furthermore, BIT225 inhibited HIV-1 replication in monocyte derived DCs and prevented the infection of co-cultured CD4+ T cells." (PMID 34834972, 2021). "Moreover, the frequency of CD38 and HLA-DR-coexpressing TIGIT+NK and TIGIT−NK cells, correlated positively with HIV-1 viral load, but had fewer CD4 T-cell counts in the first, third and twelfth month of infection." (PMID 33717085, 2021). "Thereby, type I IFNs affect CD4 T cell priming dependent on the stage of infection." (PMID 34659236, 2021). "NK‐cell subset distribution and the expression of activating and inhibiting receptors (NKp30, NKG2A and NKG2D) show strong association with the CD4/CD8 ratio and other infection‐related parameters (i.e., age at treatment initiation, time on ART and CD4+ T‐cell nadir)." (PMID 34672108, 2021). "This might be achieved by inducing resident CD8+ (or CD4+) T cells, which can quickly migrate into the epidermis and kill infected cells or produce rapidly diffusing antiviral cytokines upon infection." (PMID 33905459, 2021). "In this study, we demonstrated that a model for CD4 cell depletion could be used to estimate the duration of infection from HIV seroconversion until diagnosis, as well as age at and year of seroconversion." (PMID 33577551, 2021). "In the influenza A virus (PR8) system it was shown that while Th1 CD4 T cell responses on their own are ineffective at promoting recovery from infection, antibodies generated through T-B cooperation were indispensable in the protective response against the virus." (PMID 33571241, 2021). "During the infection process, TIGIT expression in T cell subsets within PBMCs and spleens from the infection group decreased on the third day post infection; this trend was more obvious in CD4+ T cells, but it only lasted until the fifth day after infection in CD4+T cells within PBMCs." (PMID 33629951, 2021). "While clinical data indicate T cell lymphopenia is associated with persistent SARS-CoV-2 viraemia, some studies also indicate that infection may alter the quality and phenotype of the CD4+ T cell response." (PMID 35965490, 2021). "In the CD4+ T cell response, S protein accounted for nearly 40% of the total CD4+ T cell response in individuals recovered from symptomatic infection, which was obviously higher than the CD4+ T cell response induced by M or N (39.1% vs 26.3%, P < 0.001; 39.1% vs 33.6%, P = 0.004)." (PMID 33767156, 2021). "infection models in mice suggest that both CD4+ and CD8+ cells play a protective role, CD4+ cells being involved in response to natural route of infection (i.e., oral infection model); while CD8+ are required for protecting mice against intraperitoneal infection." (PMID 33668221, 2021). "Indeed, in mice infected with Leishmania major, the absence of this pro-apoptotic protein resulted in increased frequency of antigen-specific CD4+ T cells at later stages of infection and consequent increased resistance to this parasite." (PMID 34247195, 2021). "The PBK001 vaccine was able to induce a stronger response of CD4+ T-cell cytokines, greater numbers of proliferative and polyfunctional T cells, as well as generation of IgG memory B cells to control infection." (PMID 33986290, 2021). "Moreover, corneal herpetic lesions have an increased severity if the regulatory Foxp3(+)CD4+ Treg response is compromised from the onset of infection." (PMID 34054858, 2021).
infection (continued). "Thus, rBCG-MyHCα infection encouraged the differentiation of CD4+ T cells into Th1 and Th17 cells via DC activation." (PMID 33466825, 2021). "As the HIV BAPV4 clone maintained its infectivity, we could also measure the level of productive infection after cell–cell transfer by staining for intracellular p24 of target primary CD4 T cells at 48 h post-co-culture." (PMID 34578310, 2021). "The cytokine response of cross-reactive CD4+ T cells might be altered by the sequential infection with different DENV serotypes, leading to further elevation of pro-inflammatory cytokines contributing a detrimental immune response." (PMID 33231723, 2021). "However, shortly after the infection (day 2 p.i.), 40% of CD4+ Trm produced IFN-γ in the WT and WT/WT groups and then halved and maintained around 20% from day 5 p.i. onwards." (PMID 34564636, 2021). "Associations of CD3+, CD4+, and CD8+ T cells with major infection." (PMID 34568395, 2021). "Here, we analyzed CD4+ T cells at 4.5, 8, 12, 24, and 48 h following infection." (PMID 34154423, 2021). "Those initiating ART in the first several months of infection tended to have lower fractional replacement rates of most CD4 subpopulations, which may reflect greater CD4 recovery during ART (and less of a need for homeostatic proliferation)." (PMID 33465157, 2021). "A study showed that depletion in CD4 cells, are not capable to eliminate the infection of C. trachomatis in B cell-deficient mice." (PMID 34234859, 2021). "This poses the case that tissue macrophages may be able to maintain infection for a longer duration than CD4+ T cells." (PMID 33897659, 2021). "Evidence from humanized mice and NHPs infected with T-tropic HIV or SIV shows that infection of tissue macrophages in the spleen, central nervous system and lymph nodes may be dependent on the presence of CD4+ T cells." (PMID 33594125, 2021). "Identifying early cellular correlates of antibody production after infection is more challenging due to the difficulties in obtaining early blood samples, although we recently identified actively proliferating CD4+ T-cells as a cellular correlate of subsequent seroconversion." (PMID 34372607, 2021). "Importantly, increased colonic CD4+ T cells and lower Th17/Treg ratios pre-infection correlated with improved response to ART and lower viral burden during ATI." (PMID 34138927, 2021). "During infection, CD4 T-cells also infiltrate the TG, but their role in TG remains enigmatic." (PMID 34603296, 2021). "Finally, we found that CD4+ T cell help was needed to generate functional CD8+ T cells after i.n. infection." (PMID 33508041, 2021). "The role of CD4+ T cells during hMPV infections has been poorly addressed to date." (PMID 33809875, 2021). "While the activation of CD4 T cells into mature Th1 or Th2 helper cells is a complex process that involves many factors in addition to those listed here, in the context of infection with microorganisms, the infectious challenge dose has been shown to play a significant role." (PMID 33804381, 2021). "SHIV.C.CH848 infection resulted in acute depletion of peripheral CD4+ T cells and persistent viral infection, as indicated by detectable proviral DNA even after 6 months of combined antiretroviral therapy (cART) treatment, and viral rebound after cART interruption." (PMID 33568508, 2021). "A widely accepted view is that after infection occurs in activated CD4+ T cells, a tiny fraction of the infected cells survive viral cytopathic effect and host immune elimination and revert to a more resting and memory phenotype, becoming latently infected cells." (PMID 33835029, 2021). "Additionally, an increased frequency and number of steady-state splenic CD4 T cells that express IL-17 upon polyclonal stimulation was found in mice from CC-RIX lines with low lung viral loads at day 2 post-infection." (PMID 33513210, 2021). "Reduction in the number of CD4 cells makes it hard for the body to fight off infections." (PMID 34046145, 2021).